TRAV8-4 (T cell receptor alpha variable 8-4)
Description:
V region of the variable domain of T cell receptor (TR) alpha chain that participates in the antigen recognition. Alpha-beta T cell receptors are antigen specific receptors which are essential to the immune response and are present on the cell surface of T lymphocytes. Recognize peptide-major histocompatibility (MH) (pMH) complexes that are displayed by antigen presenting cells (APC), a prerequisite for efficient T cell adaptive immunity against pathogens. Binding of alpha-beta TR to pMH complex initiates TR-CD3 clustering on the cell surface and intracellular activation of LCK that phosphorylates the ITAM motifs of CD3G, CD3D, CD3E and CD247 enabling the recruitment of ZAP70. In turn ZAP70 phosphorylates LAT, which recruits numerous signaling molecules to form the LAT signalosome. The LAT signalosome propagates signal branching to three major signaling pathways, the calcium, the mitogen-activated protein kinase (MAPK) kinase and the nuclear factor-kappa-B (NF-kB) pathways, leading to the mobilization of transcription factors that are critical for gene expression and essential for T cell growth and differentiation. The T cell repertoire is generated in the thymus, by V-(D)-J rearrangement. This repertoire is then shaped by intrathymic selection events to generate a peripheral T cell pool of self-MH restricted, non-autoaggressive T cells. Post-thymic interaction of alpha-beta TR with the pMH complexes shapes TR structural and functional avidity.
Synonyms: TCRAV1S2; TCRAV8S4; TRAV84
Tractability: Antibody: its Gene Ontology location is reachable by antibodies, with high confidence; UniProt places it where antibodies can reach, with medium confidence; UniProt predicts a signal peptide or a membrane-spanning region. PROTAC: ubiquitination databases record sites on it.
Gene: T-cell receptor variable (V) gene on chromosome 14 (21,894,433 to 21,895,030, forward strand). Ensembl gene ENSG00000211790.
Subcellular location: Cell membrane
Pathways (Reactome):
Immune System: Co-inhibition by PD-1; Downstream TCR signaling; Generation of second messenger molecules; Immunoregulatory interactions between a Lymphoid and a non-Lymphoid cell; Phosphorylation of CD3 and TCR zeta chains; Translocation of ZAP-70 to Immunological synapse
Gene Ontology:
Molecular function: MHC protein binding; peptide antigen binding
Biological process: adaptive immune response; immune response
Cellular component: immunoglobulin complex; plasma membrane
Homologues: Paralogues in human: TRAV8-2 (92% identical), TRAV8-6 (80% identical), TRAV8-3 (67% identical), TRAV8-7 (65% identical), TRAV8-1 (64% identical), TRAV3 (59% identical), TRAV16 (54% identical).